MIR762HG (MIR762 host gene)
Gene: Long non-coding RNA gene on chromosome 16 (30,875,222 to 30,895,220, forward strand). Ensembl gene ENSG00000260083.
Diseases named in the same sentence as MIR762HG in open-access papers:
MIR762HG is named in the same sentence as 1 disease in open-access papers, as found by Europe PMC text mining. Sharing a sentence is not in itself a finding about the gene and the disease. The quoted sentences say what the papers report.
tumor (1 paper, 2022). "Based on this evaluation, LINC00877, SLC25A5-AS1, ILF3-DT, LRRC75A-AS1, LINC00324, CD27-AS1, ZFAS1, SNHG5, MIR762HG, and SNRK-AS1 were the top significantly downregulated tumor suppressor candidates in MCL cases." (PMID 36359790, 2022).